YWHAE (tyrosine 3-monooxygenase/tryptophan 5-monooxygenase activation protein epsilon)
Diseases named in the same sentence as YWHAE in open-access papers (continued):
Sharing a sentence is not in itself a finding about the gene and the disease.
cancer (29 papers, 2013 to 2025). A tumor composed of atypical neoplastic, often pleomorphic cells that invade other tissues. "The reduced YWHAE expression has been described in many cancers, suggesting that the regulation of YWHAE is associated with cellular processes related to cancer cell survival and growth." (PMID 31438886, 2019). "Taken together, the results described in the present study demonstrate that YWHAE and HE4 are interacting proteins, and that YWHAE is significantly associated with advanced stage cancers and poor patient outcomes." (PMID 34107979, 2021). "The cancer samples of patients with late-onset tumors presented higher YWHAE and MYC expression and lower CDC25B expression in relation to to early-onset GC samples (p<0.05 for all analyses)." (PMID 27863420, 2016). "Reduced YWHAE expression was described in different types of cancer, including lung, larynx, and brain cancers." (PMID 27863420, 2016). "Unlike YWHAG‐deficient cancer cells, YWHAE or YWHAH deficiency did not affect EMT induced by DMOG and TGF‐β." (PMID 37759388, 2023). "Reduced YWHAE expression has also been described in other cancers, suggesting that this protein may play a role as a tumor suppressor." (PMID 27863420, 2016). "In addition, the pharmacogenomic study of the DEPs in GSCA also showed that the downregulation of proteins such as PRDX4, GDI1, and YWHAE and the upregulation of proteins such as CLEC3B, KRT38, KRT37, and HNRNPCL1 were linked to higher sensitivity toward 30 pan-cancer CTRP drugs." (PMID 37900279, 2023). "However, RNAseq analysis detected a previously unknown in-frame cancer fusion transcript of genes YWHAE and JAZF1, directly supported by nine sequencing reads." (PMID 34527573, 2021). "Vimentin can regulate lymphocyte inflammatory responses and apoptosis in a cancer microenvironment by interacting with other inflammatory proteins, including heat shock protein 90 (HSP90), transmembrane protein 4 (TMP4) and 14-3-3 protein epsilon (YWHAE)." (PMID 34638469, 2021). "Orilnc1, KIMAT1, SLCO4A1-AS1, LINC01420, KRAS1P, YWHAE, PART1, MALAT1, PCAT-1, lncRNA-NUTF2P3-001 and TP53TG1 are long non-coding RNAs (lncRNAs) whose interactions with KRAS have been verified in the context of cancer." (PMID 35139853, 2022). "The Oncomine database showed that YWHAE was highly expressed in the cancer group compared to the normal tissue group." (PMID 34107979, 2021). "A strong increase in invasive capacity was also observed in cells over-expressing LTBR and YWHAE and to a lesser degree SNAI3 and GFI1, indicating that all these genes can drive EMT in more than one model system and have the potential to promote invasiveness of carcinomas." (PMID 27876705, 2016). "Indeed, 50% of ESSs do not harbor a JAZF1 and YWHAE rearrangement by FISH, which represents an insufficient examination for the characterization of these cancers." (PMID 32933053, 2020).
tumor (29 papers, 2012 to 2025). "Decreased expression of YWHAE in tumors may be associated with its tumor suppressor properties." (PMID 31438886, 2019). "In this study, we found that circSORBS1 regulates RUFY3 mRNA expression and that the RUFY3 protein targets the YWHAE protein, which in turn affects the level of apoptosis in tumour cells." (PMID 38915053, 2024). "Numerous studies have shown that YWHAE plays an important role in the regulation of apoptosis in tumour cells." (PMID 38915053, 2024). "In contrast, a decreased YWHAE expression aggravated tumor growth by potentially inducing cell proliferation, invasion, and migration." (PMID 36834640, 2023). "On the contrary, NUSAP1 and YWHAE were over-expressed in primary tumor tissues compared to the peritoneal metastatic lesions, which was in accordance with our findings from bioinformatic analysis." (PMID 35515139, 2022). "In the tumor initiation, the opposite role of YWHAE and CDC25B in gastric carcinogenesis seems to be independent of MYC expression." (PMID 27863420, 2016). "Second post-CIR time point identified cullin 7 (CUL7) and last time point acyl-coa synthetase long chain family member 4 (ACSL4) with NF2, OBSL1 and YWHAE as highly connected components, all being described or hypothesized to play roles in tumor development." (PMID 35158950, 2022). "These neoplasms demonstrate rearrangement of YWHAE and commonly harbour YWHAE-NUTM2 fusion." (PMID 33802452, 2021). "The expression of M1 genes were activated in tumor samples, such as an oncogene YWHAE." (PMID 34131148, 2021). "Based on our previous findings, we hypothesized that MYC or CDC25B up-regulation may induce YWHAE down-regulation in GC or YWHAE down-regulation would induce CDC25B up-regulation in this neoplasia, which would also contribute to MYC overexpression." (PMID 27863420, 2016). "Thus, our findings reinforce that decreasing of YWHAE expression may be important for tumor initiation, especially in diffuse-type tumors an of early-onset." (PMID 27863420, 2016). "Of these 21, we focused on 5 proteins (YWHAE, PFN1, LCP1, IGHM, CD5L) that were enriched in external CNSL cohorts, thereby supporting their utility as CNSL-enriched tumor burden biomarkers." (PMID 40321620, 2025). "The protein levels of TRIP13, YWHAE, and p-ERK were significantly higher in tumor tissues than in normal tissues." (PMID 38012658, 2023). "In conclusion, decreasing YWHAE and increasing CDC25B expression seems to be important for tumor development, especially in diffuse-type tumors of early-onset." (PMID 27863420, 2016). "We also identified YWHAE, PFN1, LCP1, IGHM, and CD5L as potential tumor burden markers." (PMID 40321620, 2025). "The second tumor harboring a MDM2 amplification had high‐grade morphology, polysomy of JAZF1, PHF1, and YWHAE but no rearrangements were reported, leading to a diagnosis of UUS." (PMID 32352245, 2020). "YWHAE expression seems to increase and CDC25B expression seems to reduce between stages I and III; however, we did not detect a significant change among tumor stages after Bonferroni adjustment (p>0.008)." (PMID 27863420, 2016).
psychiatric disorder (4 papers, 2020 to 2025). A disorder characterized by behavioral and/or psychological abnormalities, often accompanied by physical symptoms. "Although the possible mechanisms involving 14-3-3 proteins in psychiatric disorders pathophysiology remain unknown, early overexpression of YWHAE and YWHAG has been shown to impair neurodevelopment, such as neuronal migration and neurite formation in animal models." (PMID 32555255, 2020).
neurological disorders (3 papers, 2018 to 2025). "Upregulation of YWHAE has been observed in various neurological disorders." (PMID 40026247, 2025).
YWHAE also shares sentences with these, for which no sentence is quoted: hepatocellular carcinoma (6 papers); infection (5); autism spectrum disorder (3); bipolar disorder (3); breast tumors (2); COVID-19 (2); depression (2); diabetes (2); meningioma (2); neurodegenerative disease (2); psychosis (2); uterine neoplasms (2); uterine sarcoma (2); virus infection (2); vitiligo (2); alcohol use disorders (1); cardiovascular disease (1); cerebral infarction (1); Cerebral ischemia (1); clear cell sarcoma of the kidney (1); clear-cell renal cell carcinoma (1); cocaine use disorder (1); cutaneous squamous cell carcinoma (1); dementia (1); endometrial stromal tumor (1); enterovirus infection (1); escherichia coli infection (1); Ewing sarcoma (1); gastrointestinal disorder (1); Gerstmann-Straüssler-Scheinker disease (1).
A further 35 diseases each share a sentence with YWHAE in 1 paper.